EGFR (epidermal growth factor receptor)
Diseases named in the same sentence as EGFR in open-access papers (continued):
Sharing a sentence is not in itself a finding about the gene and the disease.
tumor (continued). "Notably, exosomes engineered to display immune checkpoint modulators (PD-1, OX40L) along with tumor-targeting antibodies (anti-CD3, anti-EGFR) have demonstrated potent T-cell activation and the robust suppression of EGFR-positive tumors in murine models." (PMID 40284522, 2025). "Pharmacological modulation of SIRT6 has shown therapeutic promise, with activators such as MDL-800 inhibiting proliferation and enhancing EGFR-TKI efficacy, while natural compounds like α-hederin exert anti-tumor effects through SIRT6-dependent glycolytic inhibition." (PMID 41463311, 2025). "Blockade of EGFR signaling through small-molecule tyrosine kinase inhibitors (TKI) or targeted biologics has thus far been unsuccessful in GBM treatment, which contrasts with other EGFR-driven neoplasms, such as non-small cell lung cancer (NSCLC)." (PMID 40581663, 2025). "In adjunct, the tumor did not cluster with the previously reported EGFR‐KDDs myofibroblastic neoplasms." (PMID 40178433, 2025). "Furthermore, a trispecific TCE targeting EGFR and a NY-ESO-1 showed strongly increased efficacy and anti-tumor activity compared to TCEs targeting single antigens." (PMID 40936895, 2025). "Highly sulfated polysaccharides show stronger anti-angiogenic and anti-tumor effects, as their negative sulfate groups interact with positively charged cell-surface proteins (e.g., EGFR, MMPs, VEGF/VEGFR), blocking tumor metastasis, angiogenesis, and invasion." (PMID 41378212, 2025). "STAREGFR-T cells induced almost 100% lysis of EGFR-positive tumor cells, and their cytotoxic capacity did not decline even 72 hours post-electroporation." (PMID 41341587, 2025). "N-glycosylation in the Golgi complex generates ligands for lectins, including the EGF receptor (EGFR) 63, suggesting that aberrant glycosylation may activate the EGF pathway in tumor cells." (PMID 40861802, 2025). "Consequently, even if cetuximab or panitumumab successfully inhibits EGFR, the MAPK pathway remains fully active and continues to drive CRC tumor proliferation." (PMID 40940901, 2025). "Moreover, through signaling pathways such as Nrf2, RhoA/ROCK, EGFR/PI3K/Akt, Bax, and PI3K/Akt/mTOR, BJ also suppresses tumor proliferation and metastasis." (PMID 41156537, 2025). "Particularly in EGFR-TKI resistance research, single-cell sequencing not only enables the effective classification of cell populations and the detection of subpopulations related to resistance but also provides an accurate depiction of tumor evolution." (PMID 40003951, 2025). "This composite pathway integrated multiple oncogenic mechanisms and encompassed several classical tumour related signalling pathways, inclding PI3K-AktPI3K-Akt signaling pathway, Ras signaling pathway, HIF-1 signaling pathway, and EGFR tyrosine kinase inhibitor resistance." (PMID 41006588, 2025). "Although we did not obtain the rechallenge recommendations of EGFR-TKI drug after almonertinib-induced ILD, most literatures confirm that when an EGFR-TKI is discontinued due to ILD, replacing other EGFR-TKI drugs can usually successfully control tumor progression." (PMID 40034596, 2025). "Although dPGC1 does not modulate tumor-like growth driven by other oncogenic signals such as EGFR or InR, it plays a crucial role in suppressing Yki-induced overgrowth." (PMID 41343573, 2025). "We have used a simplified PRESSING panel based on the available tumor molecular alterations for the cohort of patients enrolled in the PETACC-8 clinical trial, but the optimal patient selection for EGFR blocking strategies in the adjuvant setting still needs to be defined." (PMID 41167084, 2025). "This interaction is also pivotal for tumor progression in cancers with WT-RAS, as evidenced by EGFR-mutant lung adenocarcinoma mice harboring PI3Kα-T208D/K227A mutations, where disrupting this interaction inhibits tumor onset and promotes significant tumor regression." (PMID 39788953, 2025).
tumor (continued). "Similarly, cetuximab, an EGFR inhibitor, improves C-REV distribution and inhibits angiogenesis, leading to tumor regression in HT-29 xenografts." (PMID 40927720, 2025). "Existing literature suggests that MAN manifestations are mediated by tumor-secreted peptide growth factors (e.g., transforming growth factor alpha [TGF-α]) that activate the epidermal growth factor receptor (EGFR) to induce epidermal hyperplasia and pigmentation." (PMID 41357602, 2025). "To test the hypothesis that F9H4 inhibits tumor growth, we engineered LLC1 to express human EGFR (hEGFR) to allow the labeling by cetuximab." (PMID 41219228, 2025). "In addition to its enzymatic activities, NT5E modulates pathways, including the EGFR/Akt and VEGF/Akt pathways, which negatively affect anti-tumor immunity." (PMID 40612859, 2025). "Our research significantly expands the understanding of TNNC1’s role in LUAD, particularly by revealing the association between TNNC1 and EGFR-TKI resistance and tumor-associated macrophage polarization, areas not explored in previous studies." (PMID 40433361, 2025). "The studies approved that PRMT5 could orchestrate EGFR and AKT networks to promote EMT in the tumor cells." (PMID 39994841, 2025). "EGFR and IDH1 were highly expressed in tumor cells, FAP and COL1A1 were confined to fibroblasts, CD68 and ITGAM marked macrophages, PECAM1 and CDH5 identified endothelial cells, OLIG2 and MOG were specific to oligodendrocytes, while CD4 and CD3D defined T-cell subsets." (PMID 41208987, 2025). "Epidermal growth factor receptor (EGFR/ErbB1/HER1) and other members of the ErbB family, including ErbB2/HER2, ErbB3/HER3, and ErbB4/HER4, are receptor tyrosine kinases that play critical roles in tumor progression across various types of cancer." (PMID 40445424, 2025). "PCBs’ binding to EGF, as observed in our docking results, may stabilize EGFR-EGF interactions, prolonging MAPK/ERK and PI3K-Akt signaling, which drives proliferation and metabolic adaptation in tumor cells." (PMID 40584614, 2025). "During EGFR-TKI treatment, tumor cell metabolic patterns undergo dynamic changes." (PMID 40486879, 2025). "Moreover, EGF-driven EGFR activation also up-regulated CD274, suggesting a role for HER family signaling in promoting immunosuppression within the tumor microenvironment." (PMID 40642068, 2025). "Actually, EGFR, ERK, STAT3, and FAK1 are also dominant players in tumorigenesis, we supported that TC2N upregulated phosphorylation levels of these oncoproteins, which in turn conferred oncogenic signals to promote tumor initiation." (PMID 39849581, 2025). "DARPPC tumor protein expression was significantly positively correlated to EGFR expression, although the strength of the correlation was not high." (PMID 40969344, 2025). "In patient-derived xenograft (PDX) mouse models, treatment with EGFR-specific CAR-T cells inhibited tumor growth without affecting body weight, demonstrating their potential efficacy against TNBC." (PMID 40281554, 2025). "Patients with high CD73 expression (≥ 50%) on the tumor cells showed improved progression-free survival (PFS) and OS, particularly in EGFR-mutant NSCLC patients receiving immune checkpoint inhibitors (ICIs) targeting programmed cell death protein 1 (PD-1) and its ligand PD-L1." (PMID 41188606, 2025). "CD44 is a putative cancer stem cell biomarker and may interact with EGFR, CD109, and EGFRvIII to facilitate the tumour progression and resistance to therapies." (PMID 40227788, 2025). "GM‐protac could induce EGFR degradation and increase the acetylation level of H3 by HDAC inhibition in lung tumor tissues, validating their potent anti‐tumor effect." (PMID 40842076, 2025).
tumor (continued). "This prediction was rigorously verified by Western blot experiments: IPTF can specifically inhibit the activation of key phosphorylation sites of AKT (Ser473), EGFR (Tyr1068), and ERK (Tyr204), thereby synergistically blocking the malignant proliferation process of tumor cells." (PMID 41008250, 2025). "Subsequently, Western blot analysis of tumor tissue lysates from A549-BRG1 tumors revealed reduced pEGFRTyr1068, EGFR, and vimentin expression, which was further attenuated following gefitinib treatment (p < 0.05), relative to their expression levels in gefitinib- and DMSO-treated A549-Puro tumors." (PMID 41514577, 2025). "Epidermal growth factor receptor (EGFR), a member of the ErbB receptor tyrosine kinase family, contains tumor-specific epitopes within its extracellular domain and is mutated or overexpressed in over 60% of NSCLC cases, promoting tumor proliferation and metastasis." (PMID 40904467, 2025). "These indications can vary with regards to squamous or non-squamous NSCLC, tumour proportion score (TPS) (PD-L1 expression of ≥ 1%; 0–49%; or ≥ 50%), with or without EGFR/ALK mutations, first- or second line, mono- or combination therapy." (PMID 39212880, 2025). "In contrast, the combination therapy showed little effect on the tumor volume of PDX#18 as these tumors had low EGFR–YAP as drug targets, which did not impact agrin." (PMID 40165020, 2025). "The epidermal growth factor receptor (EGFR) gene is a tyrosine kinase receptor located on chromosome 7p11-p13, participating in key signaling pathways responsible for the cell cycle, growth, proliferation, migration, and survival of tumor cells." (PMID 40061015, 2025). "EGFR (Epidermal Growth Factor Receptor) overexpression, driven by hypomethylation, activates oncogenic pathways such as RAS/RAF/MEK/ERK and PI3-K/Akt/mTOR, which promote tumor proliferation, survival, angiogenesis, and resistance to therapy." (PMID 40881676, 2025). "Moreover, USP11 inhibition by mitoxantrone significantly impaired EGFR- and TLR-driven tumor growth, highlighting USP11 as a potential therapeutic target." (PMID 41419456, 2025). "Disappointingly, no tumor uptake was observed in EGFR-positive tumor-bearing mice, with most activity being accumulated predominantly in the liver, gall bladder, kidneys, and spleen." (PMID 39860082, 2025). "Moreover, HIF activity also impacts epidermal growth factor receptor (EGFR) signaling, a key driver of tumor progression in GBM, where each tumor cell expresses more than 1 × 106 EGFR molecules, which is higher than the physiological contents." (PMID 41155273, 2025). "Primary resistance is the failure to achieve clinical benefit from anti-EGFR therapy by pre-existing tumor features or genetic alterations that activate downstream signaling independent of EGFR stimulation." (PMID 40940901, 2025). "Notably, researchers have engineered a nucleic acid nanogel for miR-34a which is targeted to cancer cells using anti-epidermal growth factor receptor (EGFR) Nbs, which led to a robust anti-tumor effect." (PMID 40758119, 2025). "Targeting EGFR slowed tumor growth but did not eradicate HCC1954 tumors due to the low EGFR levels in this cell line." (PMID 40614208, 2025). "A growing body of evidence reveals that resistance is not random but rather driven by a complex network of molecular alterations that sustain tumor growth independent of EGFR signaling." (PMID 40940901, 2025). "The evidence of EGFR‐KDD corroborates the recent identification of this alteration as a molecular driver in CPMT, further supporting its potential relationship with CMN and the rare myofibroblastic neoplasms of soft tissue with this molecular alteration." (PMID 40178433, 2025). "As DNA repair is intricately connected to the development of drug resistance in tumor cells 46, it could be inferred that PRDX1 may influence the sensitivity of EGFR-TKI treatment in LUAD patients via genomic instability." (PMID 40303499, 2025).
tumor (continued). "Lack of sufficient tumor tissue from the clinical trial precluded correlation of baseline PD-L1, EGFR, and CD47 expression with response, and precluded posttreatment assessments." (PMID 41171165, 2025). "Considering the results of this study, it is likely that EGFR activation also contributes to SIP growth, and that EGFR inhibitors or molecularly targeted drugs against HB-EGF may suppress tumor proliferation." (PMID 41346909, 2025). "For somatic copy number alterations, cases with high PLK3 expression not only demonstrated significant amplification peaks for PIK3C2B, PDGFRA, EGFR, and CDK4, which are defined as oncogenic drivers, but they also showed deletion peaks for tumor-suppressor genes, such as CDKN2A and CDKN2C." (PMID 39866232, 2025). "Personalized drug screening with organoids presents a viable method to determine tumor sensitivity to unique EGFR inhibitors without extensive personalized sequencing." (PMID 41155119, 2025). "Additionally, TAK-981 is being investigated in combination with immunotherapy (avelumab) and anti-EGFR antibodies for solid tumors (NCT04065555), with a particular focus on its role in modulating the tumor microenvironment." (PMID 40308776, 2025). "As an example from other tumor entities, we were able to demonstrate an adaptive response to EGFR inhibition or HER2 inhibition, leading to a rapid, compensatory counter-upregulation of the respective heterodimerization partner, HER2 or EGFR, respectively." (PMID 39864337, 2025). "As for other targeted drugs, EGFR-TKI treatment provokes over time the emergence of resistant clones, which can be present before the therapy begins or originate de novo from pools of tolerant/persister cells, eventually resulting in tumor relapse." (PMID 40846697, 2025). "The piggyBac transposon vector used for gene modification of T cells expresses a T-cell receptor specific to the WT1 tumour antigen, an NFAT promoter-regulated CAR specific to GM-CSF receptor, a CD3xCD33 bispecific T-cell engager, and a truncated EGFR suicide gene system." (PMID 40735486, 2025). "In addition, sitagliptin also limited tumor growth and led to the shrinkage of MRD tissues in vivo when combined with EGFR‐TKIs." (PMID 40479551, 2025). "This project contributes to a deeper understanding of the molecular mechanism of tumor microenvironment mediated EGFR-TKI resistance in NSCLC, and provides theoretical basis and experimental data for the development of novel resistance reversal agents against the tumor microenvironment." (PMID 40703348, 2025). "While ICG is non-specific, IRDye800 CW is often conjugated to tumor-specific anti-epidermal growth factor receptor (anti-EGFR) antibodies, such as panitumumab or cetuximab." (PMID 40380992, 2025). "Additionally, NONO's LLPS has been shown to facilitate the recruitment and enhance the interaction between the epidermal growth factor receptor (EGFR) and DNA‐PK, thereby promoting DNA repair processes and enabling tumour cells to develop radioresistance." (PMID 40211955, 2025). "KRAS mutations, unlike EGFR and ALK, are associated with a history of smoking, high PD-L1 expression, and a high tumor mutational burden (TMB)." (PMID 40558308, 2025). "The novel USP8 variant (P681Q) found in the contra-lateral tumor led to increased POMC transcription although weaker than the well characterized hotspot variant S718P, and did not affect EGFR ubiquitin." (PMID 40544420, 2025). "Mechanistically, capsaicin suppresses EGFR-mediated downstream signaling cascades, including FAK/AkT, PKC/Raf/ERK, and p38 MAPK pathways, as well as AP-1 transcriptional activity, leading to a marked reduction in MMP-9 expression and tumor cell migration." (PMID 40728967, 2025). "Tumor‐adjacent normal tissue areas were not investigated in the present cohort; only wild‐type, EML4–ALK‐rearranged, KRAS‐mutated, and EGFR‐mutated LUAD samples were compared." (PMID 40621945, 2025).
tumor (continued). "Notably, the CD45− tumor cell population exhibited enhanced sensitivity to EGFR inhibitors compared with the CD45+ immune cell population, highlighting the importance of isolating pure tumor cell populations for accurate drug response assessment." (PMID 40525275, 2025). "Moreover, sorafenib can also affect tumor angiogenesis through VEGFR and PDGFR inhibition, and different studies have shown that co-treatment of EGFR-TKIs with antiangiogenic drugs can improve progression-free survival of NSCLC patients." (PMID 40846697, 2025). "AXL is known to be involved in tumor cell growth, metastasis, and drug resistance and has been shown to bind to members of the EGFR and HER families, including MET, to promote EGFR signaling and contribute to EGFR-TKI resistance." (PMID 40224214, 2025). "Without the added impact of tobacco smoking, these tumours have quieter genomes than their EGFR counterparts." (PMID 41509216, 2025). "miR-30b can inhibit the PI3K/AKT (phosphoinositide 3-kinase/protein kinase B) signaling pathway through the regulation of EGFR, AKT, Derlin-1, GNA13), SIX1, and other target genes, thus inhibiting the epithelial–mesenchymal transition process of tumor cells and promoting apoptosis." (PMID 40075907, 2025). "The epidermal growth factor receptor (EGFR) binds to and phosphorylates Y393-AGO2 in response to hypoxia, reducing the interaction between AGO2 and DICER and inhibiting the processing of tumor-suppressing miRNAs." (PMID 40863728, 2025). "miR-34 family members induce multiple tumor-suppressive effects, including the inhibition of cell migration, cell cycle arrest, and promotion of apoptosis by directly targeting key oncogenes such as CCNE1, EGFR, and SIRT6." (PMID 41465462, 2025). "It is worth noting that inhibiting EZH2 may lead to resistance to EGFR-TKIs in NSCLC,136 and impact the tumor microenvironment, enhancing anti-tumor immunity." (PMID 40083325, 2025). "Thus, patients whose tumours have EGFR CNG and/or EGFR protein overexpression represent a subgroup that potentially benefits from EGFR inhibitor monotherapy, (HR for death, 0.21; 95% CI, 0.07 to 0.64; P = 0.006)." (PMID 40615716, 2025). "Targeting both EGFR and VEGF-A via a bispecific antibody binding potentially enhances anti-tumor activity not only by inhibiting EGFR signaling in OC, but also by blocking angiogenic activity in endothelial cells that support tumor growth and progression." (PMID 40969763, 2025). "In macrophages, EGFR activation modulates their polarization (e.g., promoting M2 polarization via PPARγ‐mediated metabolism), cytokine secretion (e.g., HB‐EGF, IL‐6), and infiltration, thereby supporting tumor progression and inflammation." (PMID 40859900, 2025). "The results showed that the peptide-conjugated IONPs enhanced tumor cell uptake compared to non-targeted IONPs, with Pep5 increasing internalization in EGFR-overexpressing cells." (PMID 40906195, 2025). "This makes ErbB receptors, particularly EGFR, key targets for targeted therapies, such as CAR-T cell therapy, which could help disrupt these signaling networks and potentially halt tumor growth." (PMID 40312353, 2025). "Additionally, it inhibits epidermal growth factor receptor (EGFR) activity and induces apoptosis in tumor cells." (PMID 40248074, 2025). "Lapatinib is a potent dual inhibitor of EGFR and HER2 tyrosine kinases; it inhibits the tyrosine kinase activity of these receptors, thereby preventing signal transduction, proliferation and survival of tumour cells." (PMID 40156167, 2025). "Recent advances have demonstrated the potential of EGFR-targeting peptides conjugated to imaging probes for non-invasive, real-time in vivo tumor detection, precision therapy, and surgical guidance." (PMID 40906195, 2025).